BRCA1 (BRCA1 DNA repair associated)
Diseases named in the same sentence as BRCA1 in open-access papers (continued):
Sharing a sentence is not in itself a finding about the gene and the disease.
colon carcinoma (continued). "Further corroborating this notion, 152 over-expressed miRNAs were present in colon cancer EVs and the uptake of these miRNAs was correlated with down-regulation of their respective mRNA targets in the transformed BRCA1-KO fibroblasts." (PMID 31200749, 2019). "Overexpression of BARD1β in colon cancer cell lines, such as in Caco-2 cells, impairs error free HR DNA repair by negatively influencing functions of BRCA1 thus sensitizing cells to PARPi." (PMID 27197561, 2016). "This was associated with an increase in EMT, as well as colony formation and enhanced cell migration, supporting that oncogenic properties of BARD1β in colon cancer are at least in part, via targeting BRCA1 function." (PMID 27197561, 2016). "BARD1β sensitizes colon cancer cells to poly ADP ribose polymerase 1 (PARP-1) inhibition even in a FL BRCA1 background." (PMID 27197561, 2016). "Overexpression of BARD1β in PARPi-resistant colon cancer cells rendered these cells sensitive to PARPi, and decreased E3 ligase activity as well as nuclear localization of BRCA1." (PMID 27197561, 2016). "All tested colon cancer cell lines are known to have wild type BRCA1 and all express FL BRCA1 protein." (PMID 27197561, 2016). "It has been shown that HIF-1α transcriptional machinery activated by hypoxia signaling pathway abrogates c-Myc activation of BRCA1 expression in colon cancer cells." (PMID 21668996, 2011). "Likewise, EVs from HT29 colon cancer cell supernatant and serum of patients with colon cancer induced transformation in BRCA1-knockout fibroblasts in vitro, and EV from osteosarcoma culture induce cell transformation of embryonic murine fibroblasts." (PMID 38252353, 2024). "ATF6 was shown to sustain the expression of oncogenes such as BRCA1 or CIP2A (in vitro data in human colon cancer cell lines CaCO2, and SW480), as well as prevent DNA damage and to improve cancer cell viability, as observed in RKO and HCT116 colon cancer cell lines." (PMID 36902344, 2023). "However, the new finding of this study is that it shows for the first time that ATF6 arm of UPR plays a key role in DNA repair, by sustaining BRCA-1 expression in colon cancer cells undergoing ER stress." (PMID 35752616, 2022). "In order to better understand the mechanisms underlying the malignant transformation of BRCA1-KO fibroblasts into colon cancer cells, we further deepened the RNA analyses by profiling differential miRNA expression between BRCA1-KO fibroblasts prior and after exposure to colon cancer EVs." (PMID 31200749, 2019). "The microarray analyses performed in this study confirmed the presence of several messenger RNA and non-coding RNAs in the colon cancer EVs and established that the expression of these transcripts was altered in target BRCA1-KO fibroblasts following exposure to the same EVs." (PMID 31200749, 2019). "Typically in colon cancer, BRCA1 is wild type, but we have reported that FL BARD1 expression may be lost, which is associated with poorer outcome." (PMID 27197561, 2016). "Therefore, having observed a reduced BRCA-1 mRNA expression and a stronger ER stress in colon cancer cells treated by Thapsigargin at the dose of 30 nM, we investigated whether BRCA-1 downregulation could depend on the IRE1 alpha endoribonuclease activity." (PMID 35752616, 2022). "To verify the hypothesis that the mutated cancer genes that were transferred through the EVs might be transcribed by recipient BRCA1-KO fibroblasts, we performed RNA sequencing on colon cancer EVs, and BRCA1-KO fibroblasts prior and after exposure to colon cancer EVs." (PMID 31200749, 2019).
colon carcinoma (continued). "After confirming that EVs were responsible for the transformation of the BRCA1-KO fibroblasts into colon cancer cells, we sought to investigate the hypothesis that cancer genetic material present in the cancer EVs could be transferred and uptaken by the recipient cells." (PMID 31200749, 2019). "This discovery suggests that colon cancer miRNAs transferred through EVs to the BRCA1-KO fibroblasts might be involved in the induction of an epithelial phenotype and acquisition of metastatic features in BRCA1-KO fibroblasts." (PMID 31200749, 2019). "It is reported that BRCA1 is expressed in many tissues, such as the lymph nodes, skin, bladder, cervix, liver, uterus, prostate, pancreas, lung, kidney, bone, brain, and is related to various types of cancer, including breast, ovarian, endometrial, pancreatic, prostate, and colon cancers." (PMID 29492227, 2018). "A BRCA1 mutation has been shown to be associated with an increased risk of early onset colon cancer in a defined population but does not seem to increase the overall risk of colon cancer." (PMID 22312502, 2011). "One-third of the BRCA1- and MGMT-methylation-positive patients had a strong family history of cancer, including breast, ovarian, and colon cancers." (PMID 38542081, 2024). "However, while recent reports have linked constitutional normal tissue promoter methylation of BRCA1 and MLH1 to ovarian and colon cancer risk, the role of epigenetic alterations as cancer risk factors remains largely unknown, presenting an important area for future research." (PMID 32859265, 2020). "Subsequently, in different studies we established the legitimacy of the hypothesis by showing that BRCA1-KO fibroblasts would turn into colon cancer cells when exposed to EVs isolated either from sera of patients with colon cancer or EVs isolated from conditioned media of a colon cancer cell line." (PMID 31200749, 2019). "Overall, we identified 75,163 SNV in the colon cancer EVs sample, 152,567 SNV in the merged BRCA1-KO fibroblasts samples and 154,729 SNV in the merged exposed BRCA1-KO fibroblasts samples." (PMID 31200749, 2019). "Decreased expression upon KRT23 knockdown was confirmed at the protein level for key molecules MRE11A, E2F1, RAD51 and BRCA1 and knockdown of KRT23 rendered colon cancer cells more sensitive to irradiation." (PMID 24039993, 2013). "We then evaluated whether the reduction of BRCA-1 by DPE/ceapinA7- or Thapsigargin/ceapinA7 could potentiate the cytotoxic effect of a DNA damaging agent such as Adriamycin, widely used to treat colon cancer." (PMID 35752616, 2022). "Indeed, BRCA-1 downregulation was counteracted by the IRE1 alpha endoribonuclease inhibitor 4μ8c, that also prevented DNA damage in Thapsigargin-treated colon cancer cells." (PMID 35752616, 2022). "In addition, we found that celastrol impaired the ability of colon cancer cells to repair DNA by reducing the expression of both PARP1 and BRCA1 genes." (PMID 35326523, 2022). "Our data indicate that the abundance of TopBP1 and BRCA1 correlates with Claspin, Timeless, and CHK1 in colon cancer cell lines, which would be consistent with the latter hypothesis." (PMID 30796221, 2019). "Also, in human colon cancer cells, HIF-1α was shown to inhibit BRCA1 activity indirectly by counteracting C-MYC under hypoxic and normoxic conditions, while BRCA1 was found to enhance hypoxia-induced stabilization of HIF-1." (PMID 29755367, 2018). "As the role of BRCA1/BARD1 in DDR might be ubiquitous and significant to different cell lines, such as neurons and colon cancer cells, the model proposed here might be relevant to different cellular backgrounds." (PMID 29180510, 2018). "Despite searching for similar genes in colon cancer, none have been found with the significance of BRCA1." (PMID 23840520, 2013). "BRCA1-KO fibroblasts were then treated or not with colon cancer EVs for 6 weeks." (PMID 31200749, 2019).
colon carcinoma (continued). "Notably, 9063 SNV were present in the colon cancer EVs RNA and in the exposed BRCA1-KO fibroblast RNA but not in control BRCA1-KO fibroblasts." (PMID 31200749, 2019). "We recently reported that BRCA1-KO cells were able to “sense” neoplastic factors in the serum of patients with cancers even at early stages and turn malignant regardless of the presence of positive tumor markers (i.e. pancreatic cancer in situ and early colon cancer with negative CEA)." (PMID 28854931, 2017).
familial breast cancer (73 papers, 2003 to 2024). "Clinically, the patient was strongly suspected to have familial breast cancer due to BRCA1 or BRCA2 pathogenic variants." (PMID 39138315, 2024). "Germ-line mutations in BRCA1 gene are related to about 25% of familial breast cancer, while somatic inactivation of BRCA1 is detected in up to 5% of sporadic breast cancers." (PMID 36631481, 2023). "In our result, the variant rate of BRCA1/2 in familial breast cancer (FBC) samples was 44.4% (8/18)." (PMID 36140642, 2022). "It is well known that mutations of BRCA1 proteins are responsible for familial breast cancer, whereas a low level of BRCA1 gene expression is associated with sporadic breast cancer." (PMID 31963223, 2020). "Hereditary familial breast cancer tends to have an early onset, particularly in those with BRCA1/BRCA2 mutations." (PMID 28894168, 2017). "BRCA1 is famous as cancer susceptibility gene in familial breast cancer, and during preclinical research, depletion of BRCA1 impaired differentiation but promoted proliferation of mammary epithelial cells." (PMID 27285752, 2016). "The frequency of ANXA1 positive tumors was higher in familial breast cancer patients with BRCA1/2 mutations than in BCAC patients, with 48.6 % versus 12.4 %, respectively; P <0.0001." (PMID 26137966, 2015). "G199R, which was observed in BRCA-1 associated familial breast cancer, shows reduced activity in yeast transactivation capacity assays." (PMID 21892948, 2011). "We conclude from our study that BRCA1 5382insC founder mutation was detected in the studied Egyptian familial breast cancer (FBC) female patients with 5% carrier frequency that was comparable to worldwide frequencies, but lower than those reported from earlier Egyptian studies." (PMID 32102521, 2020). "Mutations in RECQL gene identified in the 448 BRCA1/2-negative familial breast cancer patients." (PMID 25945795, 2015). "Our results raise the possibility that methylation and associated silencing of BRCA1 could represent a germline alteration that underlies some cases of familial breast cancer." (PMID 18269736, 2008). "BRCA1 and BRCA2 are well-known genetic factors involved in DNA repair and are associated with a strong predisposition for early-onset familial breast cancer." (PMID 37483962, 2023). "In the model proposed in the present study, the classification of five types of cancers simultaneously was enhanced with ‘Non BRCA1/BRCA2 familial breast cancer’, also a class under study, yielding a recall value of 0.92 and precision of 0.89." (PMID 36401182, 2022). "In familial breast cancer, BRCA1 and BRCA2 have been the primary targets in Latin American studies, and one of their main achievements is the detection of new variants only present in those populations." (PMID 33126731, 2020). "The inheritance of mutated suppressor genes, such as BRCA1 and BRCA2, is acknowledged as an etiological factor in hereditary breast carcinoma (HBC)." (PMID 31518337, 2019). "Since BRCA1 epigenetically inhibits miR-155, it is appropriate to test the function of miR-155 in familial breast cancer." (PMID 28562349, 2017). "Germline mutations in the BRCA1 and BRCA2 genes are the most frequent known hereditary causes of familial breast cancer." (PMID 27149669, 2016). "CtIP plays an important role in homologous recombination (HR)–mediated DNA double-stranded break (DSB) repair and interacts with Nbs1 and BRCA1, which are linked to Nijmegen breakage syndrome (NBS) and familial breast cancer, respectively." (PMID 23468639, 2013).
familial breast cancer (continued). "The potential importance of the E3 ligase activity of BRCA1 in cellular pathways is supported by the observation that missense mutations within RING finger domain of BRCA1, which cause familial breast cancer, abolish the E3 activity." (PMID 23388117, 2013). "Founder effects have been observed in the Galician population for some genetic diseases, including BRCA1 in familial breast cancer." (PMID 22238615, 2012). "To understand how BRCA1 mutations affect TGF-β1-mediated transactivation, we examined several mutants of BRCA1 that are frequently seen in BRCA1 familial breast cancer patients." (PMID 19768112, 2009). "Evidence from multiple sources strongly indicate that impairment of BRCA1 pathways is responsible for this phenotype, implying the importance of BRCA1 not only in familial breast cancers but also in sporadic cancers." (PMID 18179693, 2008). "BRCA1/2 genes account for approximately 25% of all cases of familial breast cancer." (PMID 31341521, 2019). "Patients with BRCA1 or BRCA2 (BRCA1/2) germline mutations often present tumors with these characteristics, but until now there are no data in the literature implicating a link between high ANXA1 expression and familial breast cancer." (PMID 26137966, 2015). "For instance, Mre11, Nbs1, ATM and BRCA1, which play critical roles in DNA damage checkpoint and DSB repair are linked ataxia-telangiectasia-like disorder (ATLD), Nijmegen breakage syndrome (NBS), ataxia-telangiectasia and familial breast cancer, respectively." (PMID 23468639, 2013). "In contrast, studies have also shown that SNP309 G/G alone does not have an effect on the risk or the onset of various cancers, including familial breast cancer in which mutations for BRCA1 or BRCA2 have not been detected." (PMID 19226467, 2009). "Indeed, this influence was mostly proposed in certain studies, especially those conducted on hereditary breast carcinoma related to BRCA1/2 genes." (PMID 18423013, 2008). "Interestingly, mutated forms of BRCA1, which are overexpressed in familial breast cancers failed to interact with ER-α and did not significantly affect the expression of VEGF." (PMID 35008272, 2021). "Furthermore, BRCA1 is involved in development of familial breast cancer." (PMID 28562349, 2017). "Importantly, the peripheral-blood expression patterns were predictive of familial breast cancer, independent of BRCA1/BRCA2 mutation status." (PMID 26538066, 2015). "However the MDM2 SNP309 G/G correlation with cancer onset age in their study seemed to be restricted to non mutant breast familial cancer cases and was not apparent in the BRCA1/2 mutation carriers." (PMID 19226467, 2009). "Two TSGs, BRCA1 and BRCA2 (BReast CAncer), are responsible for 80-90% of cases of “single gene” hereditary breast carcinoma." (PMID 31518337, 2019). "Variants that affect binding between BRCA1 and BARD1 have been linked to familial breast cancer or are non-functional in the HDR assay." (PMID 30925164, 2019).
invasive ductal carcinoma (65 papers, 1996 to 2026). "For patients with invasive ductal carcinoma, the BRCA1/2 double mutation frequency was 1.35% (28/2079), and the BRCA1/2 and PALB2 triple mutation frequency was 0.91% (19/2079)." (PMID 38439896, 2024). "After Bonferroni correction, BRCA1 tumors were most frequently associated with invasive ductal carcinoma, whereas BRCA2 tumors were more frequently associated with ductal carcinoma in situ (p < 0.001)." (PMID 36905492, 2023). "Among BC cases, women with BRCA1 mutations showed a significantly higher frequency of infiltrating ductal carcinomas (p = 0.01), ER-negative tumors (p < 0.001) and tumors with Ki-67 > 14 (p = 0.005)." (PMID 33266155, 2020). "Invasive ductal carcinoma was the most prevalent histology in both groups; however, the distribution of tumor histology differed significantly between BRCA1 and BRCA2 mutation carriers (P = 0.002)." (PMID 30820924, 2019). "The mutation/deletion rates of BRCA1/2 are 2.2% (15/680) and 3.2% (22/680), respectively, in TCGA invasive ductal carcinoma cohort." (PMID 27283966, 2016). "All the BRCA1 mutations are in TNBC cases with higher histological grades of invasive ductal carcinoma." (PMID 24961674, 2014). "Epigenetic regulation of DNMT1 was assessed in 85 invasive ductal carcinomas from BRCA1 mutation carriers." (PMID 24502362, 2014). "We found that BRCA1-associated ER+ cancers had a much more limited distribution of histologic types and were significantly more often pure invasive ductal carcinomas with a high mitotic rate than ER+ sporadic cancers." (PMID 20149218, 2010). "One of these subjects was diagnosed with a stage T1aN0M0 invasive ductal carcinoma, and later determined to be a BRCA1 mutation carrier." (PMID 16800895, 2006). "In addition, all the germline BRCA1/2 P/LP variants were found in the patients with invasive ductal carcinoma." (PMID 27257965, 2016). "About the BC with a BRCA1 mutation, the great majority were invasive ductal carcinomas." (PMID 27741520, 2016). "In addition to macroscopic changes in clinical manifestations, such as morbidity and prognosis in terms of tumor heterogeneity, tumors with BRCA1 mutation usually display invasive ductal carcinoma pathologically and have a higher incidence of myeloid carcinoma and atypical myeloid carcinoma." (PMID 35402620, 2022). "The increased expression levels of BRCA1 in invasive ductal carcinoma (IDC) compared to invasive lobular carcinoma (ILC)." (PMID 38224491, 2024). "Lobular carcinoma (occurring in breast lobules) was the second most common subtype for BRCA2 carriers (8.4%), and medullary carcinoma (a subtype of invasive ductal carcinoma) for BRCA1 carriers (9.4%)." (PMID 32481735, 2020). "With regard to the histological tumor subtypes, of the 86 with invasive ductal carcinomas, 11 patients exhibited BRCA1 positivity and 6 patients exhibited BRCA2 positivity." (PMID 30713775, 2019). "Altered BRCA1 expression was more frequent in invasive ductal carcinoma and less frequent in other tumour types, including intraductal carcinoma and lobular carcinomas (p=0.02)." (PMID 23508738, 2011). "HCC1937 is a BC cell line representing invasive ductal carcinoma without estrogen or progesterone receptors but with a BRCA1 mutation." (PMID 40572597, 2025).